AFP (alpha fetoprotein)
Diseases named in the same sentence as AFP in open-access papers (continued):
Sharing a sentence is not in itself a finding about the gene and the disease.
tumor (continued). "A high association between AFP progression and radiographic progression occurring within each tumour assessment period was also observed (OR 6.4, 95% CI 4.0, 10.3, P < 0.0001 for up to Week 6, OR 2.3, 95% CI 1.5, 3.5, P = 0.0002 for Weeks 6–12)." (PMID 29808014, 2018). "Whileliquid biopsy techniques are being developed to profile HCC circulating tumor cellsand associated cell-free DNA, serum AFP remains the most readily availablehematogenous biomarker for HCC." (PMID 29376136, 2018). "LDH is also significantly associated with gender, Child-Pugh grade, AFP, vascular invasion, and tumor size." (PMID 30687735, 2018). "Univariate Cox regression analysis showed that both death and relapse risk of HCC patients were increased with higher serum AFP, larger tumor size, late TNM stage and positive SKA1 expression." (PMID 30537941, 2018). "α-fetoprotein (AFP) is a tumor associated protein and the well-known serum biomarker used for HCC surveillance." (PMID 30217986, 2018). "Of all risk factors incorporated into the nomograms, preoperative AFP level, tumor number, tumor size, and microvascular invasion have been demonstrated to be associated with surgical prognosis of HCC." (PMID 30327670, 2018). "In this prognostic scoring system, patients with low albumin (< 36 g/dl), high bilirubin (> 17 μmol/l) or α-fetoprotein (AFP) (> 400 ng/ml), and large tumor size (> 7 cm) were associated with increased risks of death when underwent TACE." (PMID 29879928, 2018). "GSTP1 levels correlated negatively with tumor size and serum alpha-fetoprotein (AFP) in HCC patients, and higher GSTP1 levels associated with longer overall survival (OS) and disease-free survival (DFS)." (PMID 29507666, 2018). "The regression analysis showed that the two risk factors, including CK19/GPC3 expression pattern and AFP cutoff of ≥321 ng/mL, were the independent predictors of tumor recurrence." (PMID 28276470, 2017). "Conversely, higher grade was significantly associated with elevated preoperative AFP levels, tumor multiplicity, vessel invasion and advanced disease stage." (PMID 29050343, 2017). "In multivariate regression analysis, US- or CT- guided RFA was not an independent prognostic factor in tumor recurrence, but AFP >20 ng/ml and tumor number > 1 were independent risk factors in overall tumor recurrence." (PMID 28068369, 2017). "A reduced ND-1 copy number was associated with an elevated serum alpha-fetoprotein level (P=0.037), larger tumor diameter (P=0.017), presence of microvascular invasion (P=0.013) and advanced tumor stage (P=0.040)." (PMID 28714949, 2017). "Meanwhile, high PLCE1 expression among young patients with low AFP level and tumor size > 5 cm had an increased risk of death." (PMID 28418898, 2017). "An elevated AFP level and a larger tumor were also associated with a poor OS in our study, consistent with previous studies, and these values were included into the clinical staging system." (PMID 28355305, 2017). "High DJ-1 expression was significantly associated with poor OS in subgroups of AFP<200ng/ml or tumor size>5cm." (PMID 28036277, 2017). "Univariate analyses revealed that T+R treatment method, single tumor lesion, good tumor response, and lower baseline AFP were associated with better OS." (PMID 27880724, 2017). "Positive PET-status correlated significantly with tumor nodule size and total tumor diameter, whereas it tended to be associated with elevated AFP levels." (PMID 29074969, 2017). "Other significant risk factors associated with increased mortality were tumor size, AFP, GGT, positive for HBVDNA." (PMID 28700480, 2017).
tumor (continued). "Diffuse tumours (P = 0.001), invasive tumours (P = 0.002) and late stage tumours (P = 0.004) had statistically significant association of having an AFP level above 400 ng/ml." (PMID 29207969, 2017). "Pretransplant alpha-fetoprotein (p = 0.013) and total tumor volume (p = 0.008) were the independent risk factors." (PMID 28695391, 2017). "According to the pooled results, the abnormal expression of HK2 was significantly associated with some clinical parameters, such as large tumor size, positive lymph node metastasis, advanced clinical stage, and high AFP level." (PMID 28415659, 2017). "According to cox regression model, factors associated with RFS and OS include serum AFP level, tumor mass and Milan stage." (PMID 28294176, 2017). "Clinicopathological data indicated that high miR-483-5p expression were significantly associated with high P3 mRNA expression, high AFP, poor tumor differentiation, and TEPV in patients with HCC." (PMID 29245946, 2017). "Previous studies have concluded that larger tumor size and higher AFP level were associated with LTP and tumor recurrence." (PMID 28430634, 2017). "The expression level of INTS6 was significantly associated with the serum alpha-fetoprotein level (AFP, p = 0.004), pathology grade (p = 0.005), and tumour recurrence (p = 0.040)." (PMID 28899352, 2017). "Pre treatment AFP has a limited value In diagnosing nvHCC, Having a AFP value over 400 ng/ml was associated with aggressive tumour behaviour and poor prognosis." (PMID 29207969, 2017). "Late tumour stage (stage 3 and 4) was associated with a higher median AFP value compared to early stage tumours (P = 0.001)." (PMID 29207969, 2017). "PKM2 positive expression was associated with high alpha fetoprotein (AFP) level (P = 0.015), large tumor size (P = 0.003), occurrence of PVTT (P = 0.002) and advanced TNM stage (P = 0.008)." (PMID 29262861, 2017). "High PCT was significantly associated with mortality after adjusted for age, gender, tumor size, AFP, GGT, HBVDNA in multivariate Cox models." (PMID 28700480, 2017). "Prediction of microvascular invasion based on pre-transplant alpha-fetoprotein concentration, number of tumors, and size of the largest tumor was associated with AUROCs of 0.603 (SE = 0.046), 0.661 (SE = 0.042), and 0.622 (SE = 0.045), respectively." (PMID 28057916, 2017). "Performed analyses revealed that last pretransplant AFP was an independent risk factor for tumor recurrence; however, the effects varied with respect to fulfillment of different selection criteria." (PMID 27531306, 2017). "MVI was not an independent risk factor for recurrence (p = 0.307), in contrast to tumor number (p = 0.047) and size (p < 0.001), alpha-fetoprotein (p < 0.001) and poor differentiation (p = 0.039)." (PMID 28057916, 2017). "Previous researches reported that the prevalence of MVI ranged from 15% to 57% in HCC specimens and was associated with tumor size, alpha-fetoprotein (AFP) and typical image features." (PMID 27729623, 2017). "Co-expression of membranous EpCAM and nuclear β-catenin in the tumor specimens in our study population was associated with an AFP level < 1200 ng/mL after SIOPEL neoadjuvant chemotherapy, indicating improved chemosensitivity." (PMID 28851352, 2017). "The eligibility criteria for evaluating the association of AFP levels with tumor size were met by 9336 patients." (PMID 28993684, 2017). "Alpha fetoprotein (AFP) is a tumor-associated fetal protein produced by the fetal liver and yolk sac1." (PMID 28186128, 2017). "The nucleotide 31 mutation site was found to be associated with alpha-fetoprotein levels (P = 0.018) and Tumor size (P = 0.005), whereas the 529 site was associated with TNM stage (P = 0.029)." (PMID 29287068, 2017). "CYP2J2 protein levels were positively associated and sEH protein levels negatively associated with poorly differentiated tumor; as well, tumor sizes were greater and levels of alpha-fetoprotein were higher with high than low CYP2J2 level." (PMID 28030819, 2017).
tumor (continued). "MiR-500a-3p expression was positively associated with AFP expression level (P = 0.026), tumor size (P = 0.041), venous invasion (P = 0.029), distant metastasis (P = 0.006) and clinical stage (P = 0.010) in HCC patients." (PMID 28750679, 2017). "Among the patient subgroups, those classified based on AFP level (<20 and ≥20 ng/mL) and tumor grade (I and II, III) were significantly associated with UQCRH overexpression." (PMID 28332314, 2017). "A univariate analysis identified the Child-Pugh stage, tumor number, size of largest tumor, macro-vascular invasion, micro-vascular invasion, AFP and γ-GGT as significant risk factors associated with DFS." (PMID 27381639, 2016). "High miR-630 levels were negatively associated with AFP (P=0.003), tumor number (P=0.028), vascular invasion (P=0.015), Edmondson-Steiner stage (P=0.007) and BCLC stage (P=0.002) but not tumor size." (PMID 26993767, 2016). "Serum tumor markers of potential utility in cHCC-CC are CA 19–9 and AFP, which are associated with CC and HCC respectively." (PMID 26917546, 2016). "The five clinical risk factors that are preoperative AFP level >400 ng/mL, the largest tumor size > 5 cm, multiple tumor nodules, macroscopic vascular invasion, and microscopic portal vein thrombosis were chosen." (PMID 26936459, 2016). "Despite pre-HCC diagnosis AFP >20kU/L being associated with poor outcome, ‘AFP-detected’ tumours were offered potentially curative management as frequently as ‘US-detected’ HCCs; and had comparable survival." (PMID 27308823, 2016). "High serum AFP level suggests tumor vascular invasion and was associated with poor recurrence-free survival." (PMID 26901762, 2016). "Above all, baseline tumor characteristics before hepatectomy have a significant impact on patient prognosis, including serum alpha-fetoprotein (AFP) and albumin, and platelet count has been associated with tumor recurrence and OS in HCC patients." (PMID 27506942, 2016). "Tumor invasiveness also affected the diagnostic performance of AFP, PIVKA-II, and OPN, which had higher AUCs in patients with diffuse-type HCC than in those with non-diffuse HCC." (PMID 26986465, 2016). "Serum AFP is generally recognized as an important tumor marker and has specific diagnostic utilities." (PMID 27121855, 2016). "Another criticism of the UK listing criteria is that the value of AFP > 10,000 is too high, particularly as there is robust evidence that an AFP of >1000 ng/mL is associated with vascular invasion and poor tumour differentiation and hence poorer outcome." (PMID 27413539, 2016). "Level of CXCL1 protein in tumor, which was associated with AFP levels in serum and tumor differentiation, was an independent risk factor for recurrence along with AFP, BCLC classification, and TNM stages." (PMID 27542259, 2016). "Despite their success, a head-to-head comparison of diagnostic performance of the four most promising tumor markers for HCC (AFP, PIVKA-II, OPN, and DKK-1) has yet to be reported." (PMID 26986465, 2016). "We also investigated the impact of other risk factors including baseline tumor size, number of nodules, Child Pugh score, blood supply, AFP, gender, age, BCLC stage, and ECOG score on OS and TTP." (PMID 26769845, 2016). "CXCL1 expression was associated with perioperative alpha-fetoprotein (AFP) levels in the serum (P = 0.024) and tumor differentiation (P = 0.001)." (PMID 27542259, 2016). "In the present study, we find that abnormal AFP level was associated with poor pathological remission, and is the most important clinical predicator of pathologic tumor response." (PMID 26620627, 2015). "In the multivariate analysis, tumor size and microvascular invasion were associated with OS, whereas HBsAg, AFP, tumor size, and microvascular invasion were associated with cumulative recurrence." (PMID 25514599, 2015). "Pathologic examination showed that rAd/AFP-amiRG treatment caused significant destruction of the xenografted tumor." (PMID 25691059, 2015).
tumor (continued). "Other authors also reported association between AFP level and local tumor control or tumor response after SBRT for HCC." (PMID 26681337, 2015). "Spearman’ rank analysis (data not showed) showed that M/GLR was associated with AST (P < 0.001), AFP (P < 0.001), ascites (P < 0.001), tumor number (P = 0.003), diameter lesion (P < 0.001), vascular invasion (P < 0.001) and TNM stage (P < 0.001)." (PMID 26486016, 2015). "Decreased level of miR-212 was associated with high serum AFP level (P = 0.032), large tumor size (P = 0.018) and advanced TNM tumor stage (P = 0.031)." (PMID 25965836, 2015). "AFP is a useful tumor-associated antigen for the diagnosis and predicted prognosis of HCC and monitoring metastasis and tumor recurrence in HCC patients with high AFP after hepatectomy." (PMID 25638165, 2015). "The association between AFP secretion and poor clinical outcome, HCC stemness and tumor growth rate supports further testing of AFP as an immunogenic tumor-associated antigen target." (PMID 26199728, 2015). "As a result, HCCs in young patients were associated with larger tumor size, higher Edmondson grade, more frequent intrahepatic metastasis and higher AFP level." (PMID 26093092, 2015). "Alpha-fetoprotein (AFP), a tumor-associated fetal protein, has been employed as a useful marker for HCC detection and monitoring, AFP and has been purified, characterized, cloned, and sequenced for use in the clinical diagnostic laboratories." (PMID 25815363, 2015). "Intriguingly, higher IGF2BP1 mRNA level in tumor was positively correlated with higher level of α-fetoprotein (AFP), the most widely used diagnostic biomarker for HCC (P = 0.029)." (PMID 26547929, 2015). "There was a significant correlation between low peritumoral Cbl and the following factors: large tumor size, microvascular invasion, HBeAg positive and high AFP level; these factors were in turn significantly associated with worse prognosis of HCC patients." (PMID 26474280, 2015). "EIF4EBP1 protein expression in HCC tissues is significantly correlated with serum AFP (P = 0.003) and marginally significantly associated with pathological grade (P = 0.085), tumor number (P = 0.084), tumor embolus (P = 0.084) and capsulation (P = 0.073)." (PMID 25658620, 2015). "A high NLR was associated with the presence of tumor vascular invasion (OR: 1.889, 95% CI: 1.487–2.400; p<0.001) and an elevated alpha-fetoprotein level (OR: 1.536; 95% CI: 1.152–2.048; p = 0.003)." (PMID 24788770, 2014). "Univariate Cox proportional regression revealed that the following factors were significantly associated with vascular invasion: tumor size, tumor number, AFP, DCP, and AFP-L3." (PMID 25397677, 2014). "Covariates independently associated with OS were tumor metastasis, ascites, Child–Pugh class, and serum AFP level (P<0.05 for each)." (PMID 24817002, 2014). "Univariate analysis identified the following prognostic factors that predicted increased risk of mortality: tumor size, serum AFP level ≥400 ng/ml, serum ALT level, serum albumin level and TACE treatment." (PMID 25541684, 2014). "The diagnostic sensitivity of AFP is estimated at only 25% in those with tumor size of 3 cm or smaller, the resectable size, and nearly 50% in those with 3 cm or larger and specificity range from 76% to 96%." (PMID 24999482, 2014). "Nonetheless, they managed to associate CIMP status with elevated AFP level (AFP ≥ 30 μg/L), tumor metastasis, telomerase activity, tumor–node–metastasis (TNM) staging and overall survival." (PMID 24635883, 2014). "Murine AFP-encoding plasmid DNA injection “priming” followed by a “boost” with murine AFP-encoding AdV was performed in an HCC tumor model." (PMID 24708667, 2014). "Apparently, AFP is not only a diagnostic marker, but is also a growth factor that promotes tumor progression, as supported by reports that higher serum AFP is associated with increased mortality." (PMID 24993566, 2014).
tumor (continued). "A high pretreatment level of AFP has previously been reported to be associated with poorer survival, reflecting not only tumor cell proliferation but also active disease with continuous necrosis and regeneration." (PMID 24410841, 2014). "CIMP status in tumor tissues and plasma were both significantly associated with clinicopathological parameters such as AFP level, TNM staging, gender and HBV infection." (PMID 24635883, 2014). "Univariate Cox proportional regressions revealed that the following factors were significantly associated with intra-subsegmental recurrence: tumor size, AFP, DCP, AFP-L3, platelet count and anti-HCV antibody positivity." (PMID 23593129, 2013). "Univariate analysis found an association of tumor-free survival with tumor size, serum AFP ≥ 400 ng/mL, BCLC, TNM stage, invasion and metastasis, and loss of 8p12-p23.2 and 19p13.1-p13.3 (all P-values ≤ 0.025)." (PMID 24391771, 2013). "A common approach used for screening HCC in a high risk-population is to examine serum tumor markers, such as α-fetoprotein (AFP)." (PMID 24260081, 2013). "Patients with high pretreatment levels of AFP and PIVKA-II experienced a significantly higher incidence of tumor recurrence after curative treatment, associated with the more unfavorable tumor characteristics of patients with higher levels of AFP and PIVKA-II." (PMID 24455683, 2013). "More importantly, the combined GRB2 and GAB1 protein expression was significantly associated with serum AFP (P=0.01), tumor stage (P=0.006) and tumor grade (P=0.02)." (PMID 24391994, 2013). "Serum α-fetoprotein (AFP), a fetal-specific glycoprotein antigen, is the most widely used diagnostic and prognosis predictive tumor marker for patients with HCC." (PMID 23840303, 2013). "Multivariate analysis revealed that of the tumor size, AFP value and platelet count were all risk factors for both intra- and extra-subsegmental recurrence." (PMID 23593129, 2013). "Clincopathological analysis showed the decreased level of 5 hmC in HCC was associated with tumor size, AFP level and poor overall survival." (PMID 23671639, 2013). "Reduction of Fibulin-3 was associated with tumor differentiation, clinical stage and serum AFP level." (PMID 23936443, 2013). "Univariate analysis showed that increased AFP level, decreased serum albumin level, serosa involvement, and intrahepatic metastasis were closely associated with tumor recurrence after liver resection." (PMID 23618082, 2013). "Expression of Par-3 was not significantly related to most clinicopathological characteristics, but was associated with tumor multiplicity (p = 0.002), Alpha-fetoprotein level (p = 0.046) and subsequent extrahepatic metastasis (p = 0.037)." (PMID 23322019, 2013). "On the contrary, for those patients with higher AFP levels (high risk group), even assuming a similar proportion of tumor cell killing as within the first group, the absolute AFP values will decrease more." (PMID 23216929, 2012). "In HCC tissues, further correlation analysis revealed that overexpression of cytoplasmic ZEB2 was significantly associated with serum AFP levels, tumor size and differentiation (P<0.05)." (PMID 22393452, 2012). "The univariate analysis also indicated that clinical parameters including tumor size, tumor grade, number of tumor nodules and serum AFP were significantly associated with the overall survival rate." (PMID 22952874, 2012). "Only three studies reported diagnostic utility of serum GP73 compared AFP by tumor stage and the conclusions were conflicting." (PMID 22244200, 2012). "On the contrary, elder age, microvascular invasion, larger tumor size, higher serological alpha-fetoprotein (AFP), and higher AST/ALT were associated with poor disease-free survival." (PMID 22860012, 2012). "Multivariate analysis identified specific risk factors, such as AFP level > 1,000 ng/ml, tumor number ≥ 4, tumor size ≥ 5 cm, poor differentiation, and portal vein invasion." (PMID 22697061, 2012).